NNT (nicotinamide nucleotide transhydrogenase)
Description:
The transhydrogenation between NADH and NADP is coupled to respiration and ATP hydrolysis and functions as a proton pump across the membrane (By similarity). May play a role in reactive oxygen species (ROS) detoxification in the adrenal gland.
Synonyms: GCCD4
Tractability: Small molecule: a structure with a bound ligand is known; it has a high-quality binding pocket. Antibody: UniProt predicts a signal peptide or a membrane-spanning region. PROTAC: ubiquitination databases record sites on it; its protein half-life has been measured.
Gene: Protein-coding gene on chromosome 5 (43,602,660 to 43,707,405, forward strand). Ensembl gene ENSG00000112992.
Subcellular location: Mitochondrion inner membrane
Subcellular location (Human Protein Atlas): Mitochondria
Pathways (Reactome):
Metabolism: Citric acid cycle (TCA cycle)
Gene Ontology:
Molecular function: NADP binding; NAD binding; NAD(P)+ transhydrogenase (Si-specific) activity; proton-translocating NAD(P)+ transhydrogenase activity; oxidoreductase activity
Biological process: reactive oxygen species metabolic process; NADPH regeneration; proton transmembrane transport; tricarboxylic acid cycle; generation of precursor metabolites and energy
Cellular component: membrane; mitochondrion; mitochondrial inner membrane; respiratory chain complex
Genetic constraint (gnomAD): Loss-of-function variants: 39 observed, 86.56 expected, observed/expected ratio (o/e) 0.45, 90% interval 0.35 to 0.59. The upper end of that interval is the gene's LOEUF score, 0.59, which puts it in group 2 of 6, group 1 being the genes least tolerant of losing a copy. Missense variants: 1,067 observed, 1,281.1 expected, observed/expected ratio (o/e) 0.83, 90% interval 0.79 to 0.88. Synonymous variants: 433 observed, 479.93 expected, observed/expected ratio (o/e) 0.9, 90% interval 0.83 to 0.98.
Gene-disease validity (ClinGen):
ClinGen rates the evidence that NNT causes each of these diseases.
mitochondrial disease (autosomal recessive): Definitive.
Homologues: Orthologues: chimpanzee NNT (99% identical), macaque NNT (99% identical), pig NNT (97% identical), rabbit NNT (97% identical), dog NNT (97% identical), guinea pig NNT (96% identical), rat Nnt (93% identical), tropical clawed frog nnt (87% identical), zebrafish nnt (82% identical), mouse Nnt (72% identical), Caenorhabditis elegans nnt-1 (59% identical).
Diseases named in the same sentence as NNT in open-access papers:
NNT is named in the same sentence as 48 diseases in open-access papers, as found by Europe PMC text mining. Sharing a sentence is not in itself a finding about the gene and the disease. The quoted sentences say what the papers report.
glucocorticoid deficiency (8 papers, 2014 to 2025). "We described the detailed, long-term follow-up of three siblings carrying a novel disease-causing variant in the NNT gene that is associated with an isolated glucocorticoid deficiency." (PMID 35627102, 2022). "The three patients, who were homozygous for c.1575dup in the NNT gene, developed isolated glucocorticoid deficiency." (PMID 35627102, 2022). "MC2R and MRAP are adrenal zone and ACTH pathway specific, so it is unsurprising that they give rise to isolated glucocorticoid deficiency, whereas NNT and TXNRD2 are ubiquitously expressed." (PMID 29046340, 2018). "Therefore, TXNRD2 and NNT mutations result in glucocorticoid deficiency, but the exact mechanism underlying this relationship is unknown." (PMID 40726908, 2025). "The TXNRD2 mutation in this family and the other recently described FGD syndromes due to mutations in NNT and MCM4 highlight important pathogenic pathways in addition to defective ACTH signaling, causing glucocorticoid deficiency." (PMID 24601690, 2014). "Based on the presence of a micropenis and the later onset of hyperpigmentation, along with failed ACTH stimulation test and XY karyotype, we suspected the diagnosis of mutations of NR0B1, CYP11A1, and STAR genes or familial glucocorticoid deficiency (FGD) (MC2R, MRAP, NNT, and AAAS)." (PMID 36407315, 2022). "Moreover, genetic variants of NNT and TXNRD2, which are involved in maintaining the mitochondrial ROS balance, have been shown to be disease causing in several patients with familial glucocorticoid deficiency informing the importance of the mitochondrial ROS system for steroidogenesis." (PMID 38885337, 2024).
Adrenal insufficiency (7 papers, 2016 to 2026). Insufficient production of steroid hormones (primarily cortisol) by the adrenal glands. "The identification of a homozygous mutation in the NNT gene in these two siblings also adds to the growing body of evidence suggesting that defects in mitochondrial function can contribute to adrenal insufficiency." (PMID 39917159, 2025). "Single nucleotide polymorphism genotyping and targeted exome sequencing of consanguineous kindreds with adrenal insufficiency identified variants in the gene encoding the inner mitochondrial membrane enzyme, nicotinamide nucleotide transhydrogenase (NNT)." (PMID 38189052, 2023). "The sensitivity of adrenal glands to oxidative damage, is illustrated by three different rare conditions having in common adrenal insufficiency and oxidative stress: mutations in NNT, TXNRD2, or AAAS." (PMID 34867779, 2021). "Mutations in MRAP (encoding melanocortin 2 receptor-associated protein) and NNT (encoding nicotinamide nucleotide transhydrogenase) cause adrenal insufficiency without other features and can only be diagnosed by genetic analysis, as shown here." (PMID 26523528, 2016).
Glucose intolerance (7 papers, 2014 to 2024). Glucose intolerance (GI) can be defined as dysglycemia that comprises both prediabetes and diabetes. "NNT mutation or deletion impairs mitochondrial function and can lead to glucose intolerance and insulin resistance, both implicated in AD." (PMID 24655393, 2014). "The C57BL/6 strain carries mutations in the nicotinamide nucleotide transhydrogenase (Nnt) gene, which may predispose them toward glucose intolerance, and result in mitochondrial redox abnormalities." (PMID 38585221, 2024). "Furthermore, C57J mice develop glucose intolerance on a regular chow diet, a phenotype which is attributed to a loss of function mutation in the nicotinamide nucleotide transhydrogenase gene." (PMID 32733181, 2020).
heart failure (6 papers, 2019 to 2026). Inability of the heart to pump blood at an adequate rate to meet tissue metabolic requirements. "Due to a mutation of the NNT gene, the C57BL/6J mice are protected from oxidative stress, heart failure, and death." (PMID 34199098, 2021). "One consideration is the presence of a missense mutation in nicotinamide nucleotide transhydrogenase (Nnt) in the C57BL/6J strain, which has been shown to reduce oxidative stress and ameliorate heart failure induced by TAC." (PMID 31925563, 2020). "A recent study could demonstrate in detail that the defective mitochondrial transhydrogenase (NnT) in C57Bl/6J ameliorates pressure overload-induced cardiac failure because of differences in antioxidative capacity." (PMID 33205255, 2020). "They considered this was due to the pro-oxidative effect of the nicotinamide nucleotide transhydrogenase (Nnt) in the C57BL/6NCrl substrain because C57BL/6J mice lacking functional Nnt were protected from heart failure." (PMID 32699840, 2019).
hepatoma (3 papers, 2021 to 2025). "NNT deficiency was reported to decrease HDAC1 activity and increase global protein acetylation in hepatoma cells." (PMID 35626691, 2022).
Impaired glucose tolerance (3 papers, 2019 to 2025). An abnormal resistance to glucose, i.e., a reduction in the ability to maintain glucose levels in the blood stream within normal limits following oral or intravenous administration of glucose. "Loss of nicotinamide nucleotide transhydrogenase (NNT) in C57BL/6J mice has been attributed to impaired glucose tolerance, atherosclerosis, cardiomyopathy, and depressive-like behavior." (PMID 41226410, 2025).
melanoma (3 papers, 2016 to 2024). A malignant, usually aggressive tumor composed of atypical, neoplastic melanocytes. "First, mRNA levels of NNT were downregulated and upregulated after knockdown and overexpression of MITF in UACC257 melanoma cells, respectively." (PMID 39277608, 2024). "In contrast, knockdown of NNT decreases the GSH/GSSG ratio, increases the NADP+/NADPH ratio and increases eumelanin synthesis in melanoma cells." (PMID 35956878, 2022). "Melanoma cells are able to sustain NADPH levels and maintain a fairly constant NADP/NADPH ratio, most likely through other NADPH reducing reactions either by NADP-dependent malic enzymes or nicotinamide nucleotide transhydrogenase (NNT)." (PMID 26869992, 2016).
primary adrenal insufficiency (3 papers, 2018 to 2023). A hormonal disorder that occurs when the adrenal glands fail to release adequate amounts of glucocorticoids (cortisol), mineralocorticoids (aldosterone, 11-deoxycorticosterone), and androgens (dehydroepiandrosterone) to meet physiologic needs, despite release of ACTH from the pituitary. "Nicotinamide nucleotide transhydrogenase (NNT) gene deficiency has recently been shown to be involved in Primary Adrenal Insufficiency (PAI)." (PMID 36918776, 2023). "This case highlights that a specific genetic diagnosis of Primary Adrenal Insufficiency can induce fertility monitoring of patients, as nicotinamide nucleotide transhydrogenase mutation appears to have accelerated testicular damage." (PMID 36918776, 2023). "Nicotinamide nucleotide transhydrogenase (NNT) deficiency causes primary adrenal insufficiency (PAI) and possibly some extra-adrenal manifestations." (PMID 35627102, 2022). "Recent genetic studies have provided new insights into adrenal pathophysiology, revealing that inactivating mutations in the gene encoding the antioxidant enzyme nicotinamide nucleotide transhydrogenase (NNT) underlie a rare, hereditary form of primary adrenal insufficiency." (PMID 29850793, 2018).
aortic aneurysm (2 papers, 2021 to 2023). A ruptured aneurysm located in the wall of the proximal portion of the descending aorta proceeding from the arch of the aorta. "Notably, we recently demonstrated that mice with a deficiency of the mitochondrial enzyme nicotinamide-nucleotide-transhydrogenase (Nnt) are more susceptible to AngII-induced aortic aneurysms than their Nnt-proficient counterparts." (PMID 36743698, 2023).
cardiomyopathy (2 papers, 2020 to 2025). A disease of the heart muscle or myocardium proper. "The C57BL/6J and C57BL/6N mice have well-documented phenotypic and genotypic differences, including the infamous nicotinamide nucleotide transhydrogenase (Nnt) null mutation in the C57BL/6J substrain, which has been linked to cardiovascular traits in mice and cardiomyopathy in humans." (PMID 32213617, 2020).
diabetes (2 papers, 2014 to 2018). "Finally, we used C57BL6/J mice that are susceptible to the development of diabetes due to a mutation in the nicotinamide nucleotide transhydrogenase gene." (PMID 29896159, 2018). "Here, we studied metabolic functions and islet gene expression profiles of C57BL/6J mice with naturally occurring nicotinamide nucleotide transhydrogenase (NNT) deletion mutation, a widely used model of diet-induced obesity and diabetes." (PMID 24505268, 2014).
non-small cell lung carcinoma (2 papers, 2020 to 2024). A group of at least three distinct histological types of lung cancer, including non-small cell squamous cell carcinoma, adenocarcinoma, and large cell carcinoma. "Nicotinamide nucleotide transhydrogenase (NNT) is known to sustain mitochondrial antioxidant capacity through the generation of NADPH; however, its function in non-small cell lung cancer (NSCLC) has not been established." (PMID 32196080, 2020).
Obesity (2 papers, 2014 to 2020). Accumulation of substantial excess body fat. "The diet-induced obesity model most frequently used is the C57Bl6J mouse model that may be highly responsive to overfeeding, due in part to the lack of the mitochondrial enzyme, nicotinamide nucleotide transhydrogenase (NNT), needed to effectively scavenge ROS." (PMID 33178037, 2020).
Azoospermia (1 paper, 2023). Absence of any measurable level of sperm,whereby spermatozoa cannot be observed even after centrifugation of the semen pellet. "NNT deficiency has been reported to cause complete germ line loss and azoospermia." (PMID 37834450, 2023).
cognitive decline (1 paper, 2025). "Higher levels of NNT, MYO15A, and GCA were protective in females; greater expression of PEPD, CTNNBL1, MVB12A, XKR8, WBP1L, and GALNT7-DT were associated with faster cognitive decline in females." (PMID 40166028, 2025).
Fibroadenoma (1 paper, 2020). A benign tumor of the breast characterized by the presence of stromal and epithelial elements. "For fibroadenoma tissues, compared with both fibroadenoma-adjacent and normal tissues, there were six up-regulated (ANXA6, VCP, SERPINH1, galactosidase alpha, NNT, and MMP11) and 38 down-regulated (KRT10, KRT1, ALDH1A1, ECM1, and others) proteins in fibroadenoma." (PMID 33194682, 2020).
glioma (1 paper, 2022). A benign or malignant brain and spinal cord tumor that arises from glial cells (astrocytes, oligodendrocytes, ependymal cells). "SNHG18, NEAT1, LINC00339) and low expression of four lncRNAs (DICER1.AS1, NNT.AS1, WAC.AS1, TTC28.AS1 were with poor prognosis in glioma." (PMID 35237509, 2022).
hearing loss (1 paper, 2023). "We also identify four additional novel candidate genes (COL5A1, HMMR, RAPGEF3, and NNT) in which rare variant burden may be associated with hearing loss." (PMID 36656851, 2023).
Infantile encephalopathy (1 paper, 2020). Encephalopathy with onset in the infantile period. "For instance, PGK, NNT, SUCLA2, and FH have been linked to inherited disorders including, but not limited to, infantile encephalopathy, X-linked inherited disorders, myopathies, and neural tube defects." (PMID 33425810, 2020).
lung carcinoma (1 paper, 2023). "In cancer cells, dCas9-TET1 enhances the cisplatin sensitivity of A549 cells (lung carcinoma epithelial cells) by promoting the expression of nicotinamide nucleotide transhydrogenase (NNT)." (PMID 37239005, 2023).
neuroblastoma (1 paper, 2025). Neuroblastoma (NB) is the most common solid, extracranial childhood tumor. "It was shown that lactate directly activates NPAS2:BMAL1-dependent gene expression in cultured neuroblastoma cells significantly reducing NAD+/NADH ratio via lactate dehydrogenase (LDH), which in turn influences NADP+/NADPH levels via nicotinamide nucleotide transhydrogenase (NNT)." (PMID 41339276, 2025).
steatosis (1 paper, 2023). Increased lipid within the cytoplasm of cells. "In NNT-null mice, diet-induced progression of steatosis to steatohepatitis is exacerbated, relative to wild-type, NNT+/+ mice." (PMID 37884933, 2023).
tumor (8 papers, 2017 to 2025). "Our study unveiled a new mechanism by which HIF2a regulated lipid metabolism and promoted tumor progression in ccRCC; in this mechanism, HIF2a inhibits NNT expression via miR‐455‐5p to promote lipid accumulation, resulting in the progression of tumor." (PMID 33463050, 2021). "The results of tail vein metastasis models showed that NNT overexpression significantly reduced the liver metastasis of tumor cells." (PMID 33463050, 2021). "Mechanistic investigations showed that HIF2a suppressed NNT expression by activating miR‐455‐5p, which reduced the level of lipid browning‐mediated tumor cell “slimming” and resulted in ccRCC progression." (PMID 33463050, 2021). "A recent study revealed that IL-1β can regulate iron-sulfur cluster homeostasis by inducing the acetylation of the mitochondrial inner membrane protein nicotinamide nucleotide transhydrogenase, thereby inhibiting ferroptosis in tumor cells and mediating immunotherapy resistance." (PMID 40895546, 2025).
cancer (4 papers, 2012 to 2023). A tumor composed of atypical neoplastic, often pleomorphic cells that invade other tissues. "NNT silencing decreases ability of cancer cells topreserve NAD+ and NADPH levels and suppressestheir proliferation and aggressive behavior possiblyvia alteration of HIF-1α and HDAC1-dependentpathways." (PMID 31210440, 2019). "Recent studies have highlighted contribution ofNicotinamide nucleotide transhydrogenase (NNT)and the related NAT in the pathogenesis of somehuman cancer types." (PMID 31210440, 2019). "NNT is a mitochondrial enzyme that produces NADPH, and this enzyme has not been implicated in cancer so far in the literature." (PMID 27941907, 2016). "The 5p12 region harbors some important genes, for example GHR (growth hormone receptor), SEPPI, PAIP1, NNT and FGF10 that may be related to cancer (for complete list of genes in amplification regions)." (PMID 22363777, 2012).
kidney disease (1 paper, 2022). "For example, the C57BL/J mouse lacks nicotinamide nucleotide transhydrogenase (NNT) and should be used with extreme caution when the focus is studying NAD+ redox biochemistry in kidney disease." (PMID 36008971, 2022).
metabolism disorders (1 paper, 2021). "We used C57BL76J mice in the present study, which have a mutation in the NADPH-producing enzyme nicotinamide nucleotide transhydrogenase (NNT), which might cause mitochondrial dysfunction and increase susceptibility to metabolism disorders 69,70." (PMID 33754067, 2021).
NNT also shares sentences with these, for which no sentence is quoted: Adrenocortical Carcinoma (1 paper); arthropathy (1); atherosclerosis (1); bovine tuberculosis (1); breast (1); breast carcinoma (1); cyst (1); glioblastoma (1); hypertrophic cardiomyopathy (1); hypothyroidism (1); infection (1); Insulin resistance (1); lupus (1); MEGDEL syndrome (1); Micropenis (1); Miller syndrome (1); MIRAGE syndrome (1); myopathies (1); polycystic kidney disease (1); renal fibrosis (1); Sepsis (1); X-linked inherited disorders (1).